SSTR2 (somatostatin receptor 2)
Diseases named in the same sentence as SSTR2 in open-access papers (continued):
Sharing a sentence is not in itself a finding about the gene and the disease.
somatotropinomas (continued). "To better understand the lack of efficacy of the SSTR2 somatostatin analogs in NFPA, we evaluated the mRNA expression levels of ZAC1 and SSTR subtypes 1, 2, 3 and 5 in NFPA and compared them to those of somatotropinomas and normal pituitaries." (PMID 24098585, 2013). "ZAC1 and SSTR2 are underexpressed and SSTR3 is overexpressed in NFPA compared to those in somatotropinomas and in normal pituitaries, which might explain the lack of tumor shrinkage that is observed in response to commercially available SA therapy in patients with NFPA." (PMID 24098585, 2013).
nasopharyngeal carcinoma (12 papers, 2021 to 2025). A carcinoma arising from the nasopharyngeal epithelium. "Notably, SSTR2-SST has been significantly associated to higher survival rates in Epstein-Barr virus (EBV)-nasopharyngeal cancer, a class of head and neck cancer, and its targeting with a peptide-drug conjugate (i.e., PEN-221) has been proposed to treat this type of tumor." (PMID 38723607, 2024). "In view of SSTR2 diagnostic, imaging and therapeutic implications extrapolated from nasopharyngeal carcinoma studies, along with SSTR2 sensitivity and specificity for LEC, SSTR2 testing in SLECs is encouraged." (PMID 38315310, 2024). "On a different note, the methylation of the SSTR2 genes was found to be a poor prognostic factor in the case of laryngeal squamous cell carcinoma; the expression of SSTR2 in the case of nasopharyngeal carcinoma was found to be moderate to high." (PMID 39329930, 2024). "A study found a high concentration and intensity of SSTR2 when examining nine Epstein–Barr virus-positive nasopharyngeal carcinomas using immunohistochemistry." (PMID 37568733, 2023). "SSTR2 is an Epstein-Barr virus–induced druggable target in nasopharyngeal cancer, and Lechner and others demonstrated the preclinical effectiveness of targeted treatment." (PMID 37900156, 2023). "in a study of primary, recurrent, and/or undifferentiated nasopharyngeal carcinomas, showed multifocal to diffuse strong SSTR2 expression in 90% of tumors including 8 of 9 EBV-associated and one EBV-negative nasopharyngeal carcinoma." (PMID 35198446, 2022). "that showed that in EBV-driven nasopharyngeal carcinomas the expression of SSTR2 is induced by EBV latent membrane protein 1 via the NF-κB pathway." (PMID 35198446, 2022). "Besides, our previous study demonstrated that SSTR2 has a unique immunohistochemical landscape in NK-NPC and that SSTR2 expression has an important role in the diagnosis of nasopharyngeal carcinoma in clinicopathology." (PMID 37098551, 2023). "Indeed in that study 252 of 311 (81%) nasopharyngeal carcinomas expressed SSTR2 and SSTR2 expression was enriched in EBV-positive and in non-keratinizing nasopharyngeal carcinomas." (PMID 35198446, 2022).
paraganglioma (12 papers, 2021 to 2026). A benign or malignant neoplasm arising from paraganglia located along the sympathetic or parasympathetic nerves. "Nevertheless, the expression of SSTR2 renders paragangliomas, along with a host of other tumors, responsive to octreotide radioligand therapy." (PMID 39329930, 2024).
carcinoid (11 papers, 2013 to 2025). "We found that patients with carcinoid and thyroid cancer have the highest positive rate of SSTR2 IHC among 20 types of cancer (100%)." (PMID 35264912, 2022). "Typical carcinoid tumors usually have high concentration of somatostatin receptors among which octreotide binds with higher affinity to SSTR-2 and SSTR-5." (PMID 25431598, 2014). "The fact that carcinoid tumors, one of the very rare tumors that naturally overexpress SSTR2, have been imaged clinically for many years using 111In-octreotide supports the current data that imaging SSTR2-based reporters will function in patients." (PMID 23762226, 2013). "The small cell carcinoma also showed strong expression of SSTR2 in 100% of the tumor cells, the atypical carcinoid tumor showed moderate SSTR2 expression in 95% of tumor cells and the squamous cell carcinoma exhibited strong SSTR2 expression in 5% of tumor cells." (PMID 35198446, 2022). "We could not confirm that finding in TNETs as we found that only 40% of atypical carcinoid tumors expressed SSTR2 while 100% of small cell carcinomas expressed that marker." (PMID 35198446, 2022). "The expression of SSTR-2 in lung NEC with carcinoid morphology remains unclear." (PMID 31511024, 2019). "Treatment of recently established PNET cell line NT-3 and pulmonary typical carcinoid cell line H727 with 10 μM BYL719 for 48 h induced mRNA expression of SSTR2, but not SSTR5, two genes related to neuroendocrine differentiation." (PMID 38375032, 2024).
Hypoglycemia (9 papers, 2012 to 2026). A decreased concentration of glucose in the blood. "SSTR2 antagonism after recurrent hypoglycemia ameliorates the glucagon and corticosterone responses, as well as decreases the risk of insulin-induced hypoglycemia in rats with type 1 diabetes." (PMID 29342932, 2018). "First, we developed a rodent model of late-stage T2D that involved rigorous model characterization, extensive insulin titration protocols for adequate depth and duration of hypoglycemia and efficacy testing with two SSTR2 antagonist compounds." (PMID 38510652, 2024). "The HFF control group reached hypoglycemia much faster than the T2D rats following bolus insulin administration to induce hypoglycemia in both the vehicle- and SSTR2 antagonist-treated (PRL-2903) conditions." (PMID 38510652, 2024). "SSTR2 antagonists increased the glucagon response and reduced incidence of hypoglycemia, which was more pronounced with ZT-01 than PRL-2903." (PMID 38510652, 2024). "In this study, we establish a rodent model of T2D, characterize the counterregulatory response to hypoglycemia and evaluate proof of concept and efficacy of the SSTR2 antagonists PRL-2903 and ZT-01 to prevent insulin-induced hypoglycemia." (PMID 38510652, 2024). "Previous experiments in our lab assessing hypoglycemia prevention using an SSTR2 antagonist in a rodent model of recurrent hypoglycemia have also demonstrated a similar decrease in liver glycogen content with drug treatment." (PMID 38510652, 2024). "In summary, we show here that an SSTR2 antagonist can improve the glucagon counterregulatory response to insulin-induced hypoglycemia and prevent, or at least delay, the onset of hypoglycemia by up to −40 min in a rat model of T2D." (PMID 38510652, 2024). "In contrast, SSTR2 antagonism increased insulin during hyperglycemia as well as increased glucagon secretion during hypoglycemia." (PMID 33434183, 2021). "After the injection of insulin, rats became hypoglycemic, but with the SSTR2 antagonist, hypoglycemia was avoided." (PMID 22969729, 2012). "While one of the goals of this study was to assess the possible effect of SSTR2 antagonism on the efficacy of bolus insulin to restore euglycemia, the dose given may have been too high as some of the animals developed hypoglycemia in both treatment groups." (PMID 41502124, 2026). "Here, we show that, in addition to insulins, the deadly fish hunter, Conus geographus, uses a selective somatostatin receptor 2 (SSTR2) agonist that blocks the release of the insulin-counteracting hormone glucagon, thereby exacerbating insulin-induced hypoglycemia in prey." (PMID 39164229, 2024). "Hypoglycemia also occurs in late-stage type 2 diabetes (T2D), particularly when insulin therapy is initiated, but the utility of SSTR2 antagonists in ameliorating hypoglycemia in this disease state is unknown." (PMID 38510652, 2024). "In the current study, the increased time before hypoglycemia onset, and the decreased incidence of hypoglycemia following SSTR2 antagonist treatment (PRL-2903) was accompanied by a corresponding increase in plasma glucagon level and a decrease in liver glycogen content (p = 0.08)." (PMID 38510652, 2024). "At present the ideal timing or dose level for regular use of SSTR2 antagonists for the prevention of hypoglycemia remains unclear." (PMID 38510652, 2024). "The primary purpose of this study was to test the efficacy of two SSTR2 antagonists in a rodent model of T2D to see if treatment could enhance the endogenous glucagon counterregulatory response and prevent hypoglycemia during an insulin-induced hypoglycemic challenge." (PMID 38510652, 2024). "The use of novel somatostatin receptor 2 antagonists (SSTR2a) may resolve some of the dysfunction in glucagon counterregulation in diabetes, which could help to reduce the burden of treatment-induced hypoglycemia." (PMID 38298268, 2023). "One of the key questions was whether the SSTR2 antagonist can actually prevent hypoglycemia." (PMID 22969729, 2012).
Hypoglycemia (continued). "Once model verification assessments were completed and basal hormone and glucose responses determined, two SSTR2 antagonist compounds (PRL-2903 and ZT-01) were tested for hypoglycemia prevention in T2D rats and controls in two experiments." (PMID 38510652, 2024). "After the initial demonstration of SSTR2 antagonist efficacy using PRL-2903, a lower glucose nadir was targeted, to ensure that a high proportion of control rats would experience hypoglycemia." (PMID 38510652, 2024). "Collectively these responses in the SSTR2 antagonist-treated animal groups resulted in glucagon levels greater than in T2D controls and similar to those observed in HFF control response to hypoglycemia." (PMID 38510652, 2024). "We performed glucose and hormone characterization with and without SSTR2 antagonist under basal (unstimulated) and hypoglycemia-stimulated conditions in animals with and without T2D." (PMID 38510652, 2024). "We hypothesized that treatment with an SSTR2 antagonist (PRL-2903), prior to insulin-induced hypoglycemia, would increase the glucagon response to iatrogenic (i.e., insulin-induced) hypoglycemia." (PMID 38510652, 2024). "If SSTR-2, SSTR-3 and SSTR-5 are not expressed or have a low tumor expression, SSAs can lead to paradoxical hypoglycemia because they also inhibit counterregulatory hormone secretion (i.e., glucagon and growth hormone)." (PMID 34199977, 2021).
neuroendocrine carcinoma (9 papers, 2015 to 2024). A malignant neuroendocrine neoplasm composed of cells containing secretory granules that stain positive for NSE and chromogranin. "Only one other tumor, a neuroendocrine carcinoma, was observed to demonstrate more than 20% of cells staining for SSTR2." (PMID 37568733, 2023). "Neuroendocrine carcinomas (NECs) displaying SSTR2 have been found to have a more favorable prognosis and a better response to treatment using SSAs." (PMID 37568733, 2023). "The radiolabeled somatostatin analog [177Lu]Lu-DOTA-TATE has proven valuable for the treatment of SSTR2-expressing neuroendocrine cancers." (PMID 35745856, 2022). "SSTR2 has an important role in differentiated neuroendocrine carcinomas." (PMID 36365243, 2022). "The SSTR2-targeting radiopharmaceutical [68Ga(DOTATATE)] has demonstrated superior clinical resolution and sensitivity compared to the 111In-labelled SPECT tracer, [111In(DTPA-octreotide)], in identifying tumours expressing SSTR2 in neuroendocrine cancer patients." (PMID 26452495, 2015). "Unsurprising was the strong SSTR2 intensity in both the neuroendocrine carcinoma (NEC) and CXPA tumors." (PMID 37568733, 2023). "However, in Somatostatin Receptor 2 signaling promotes growth and survival in High Grade Neuroendocrine Lung Cancer, we showed that SSTR2 is highly expressed in both primary SCLC and cell lines and serves a vital pro survival role in high grade neuroendocrine carcinomas." (PMID 31413814, 2019).
diabetes (8 papers, 2020 to 2026). "This review compiles recent evidence for the role of SST receptor 2 (SSTR2) signaling in the pathophysiology of glucagon counterregulatory failure in diabetes." (PMID 38298268, 2023). "Even more recently, researchers have investigated a novel somatostatin receptor-2 antagonist, ZT-01, which they have used to stimulate glucagon release in rats with diabetes." (PMID 36992764, 2022). "Future studies should explore the possibility that this and other SSTR2 antagonists may alter hormone secretions in these tissues in rodent models of diabetes." (PMID 41502124, 2026). "This review also summarizes the non-clinical and clinical data available to date on SSTR2 antagonism as a therapeutic approach to restoring glucagon counterregulation in diabetes." (PMID 38298268, 2023). "We hypothesize that prolonged SSTR2 antagonism will not exacerbate glycemia and hormone responses in animals with diabetes." (PMID 41502124, 2026). "Selective antagonism of SSTR2 has been shown in various non-clinical models of T1D and in early phase clinical trials to at least partially restore glucagon counterregulation, with the goal of reducing hypoglycemia exposure in insulin-requiring diabetes." (PMID 38298268, 2023).
gastric cancer (8 papers, 2014 to 2024). A primary or metastatic malignant neoplasm involving the stomach. "SSTR2 was also proven to be associated with tumorigenesis in gastric cancer and breast cancer." (PMID 35264912, 2022). "To this end, we performed longitudinal PET-CT imaging of ICAM-1 CAR T cells using 18F-NOTA-Octreotide in a Hs 746T gastric cancer model, where tumor cells lack overexpression of SSTR2 on their surfaces." (PMID 38550578, 2024). "The SSTR2 expression in gastric cancer was interpreted based on the HER2 interpretation criteria outlined in the 2020 Chinese consensus on the pathological diagnosis of gastrointestinal and pancreatic neuroendocrine neoplasms." (PMID 39484039, 2024). "The immunohistochemical analysis indicated that 47.4% of HG-NENs expressed SSTR2 at a level above 1+ based on the HER2 criteria for gastric cancer." (PMID 39484039, 2024). "Data has also suggested the involvement of epigenetic mechanisms in the controlling SSTR2 expression in gastric cancer." (PMID 33085037, 2021). "Additionally, one stomach cancer patient and one skin cancer patient showed a high staining of SSTR2." (PMID 35264912, 2022). "A whole-genome bisulfite sequencing analysis revealed that the SSTR2 promoter was significantly hypermethylated in gastric tumors, dysplasia, and intestinal metaplasia compared to non-tumor tissues from patients with gastric cancer." (PMID 36551669, 2022).
thyroid cancer (8 papers, 2019 to 2024). "Our group also demonstrated a higher expression of SSTR2 in all types of thyroid cancers compared to normal thyroid based on immunohistochemical analysis of surgical tumor specimens obtained from patients with thyroid cancer." (PMID 35712243, 2022). "While several studies have demonstrated SSTR2 positivity in thyroid cancers, other studies have demonstrated a relative abundance of other SSTR subtypes, such as SSTR5, in these tumors." (PMID 35712243, 2022). "As most PRRTs utilize SSAs that bind to SSTR2, treatment of thyroid cancers that express other types of SSTRs would not be feasible with most of the currently available PRRTs." (PMID 35712243, 2022). "We measured the basal protein expression level of SSTR2 in human fibroblast cells (917 and WI38 cells), aggressive thyroid cancer cell lines (TPC, FTC236, and Hth7), and in various NET cell lines (medullary thyroid cancer: TT and MZ cells, pancreatic NE cancer: BON-1, and pulmonary carcinoid: H727)." (PMID 31163616, 2019).
colorectal cancer (6 papers, 2013 to 2024). A primary or metastatic malignant neoplasm that affects the colon or rectum. "The cancers with the next highest SSTR2 IHC-positive rates included colorectal cancer (91.7%), liver cancer (91.7%) and urothelial cancer (91.7%)." (PMID 35264912, 2022). "In colorectal cancer, SSTR2 was shown to be significantly methylated, which results in SSTR2 function loss." (PMID 35264912, 2022). "For colorectal cancer (CRC), the SSTR2 promotor was characterized by enhanced methylation levels, which was associated with reduced SSTR2 expression." (PMID 33085037, 2021). "Recent studies show that SSTR2 is significantly methylated in colorectal cancer." (PMID 35264912, 2022). "While DNA methylation in genes MDF1, SSTR2, CMTM3, TGFB2, and NDRG4 is a potential marker for the detection of colorectal cancer in the early stages of its development, hypermetylation in gene CLDN11 is associated with metastasis and poor prospect of patient survival with colorectal cancer." (PMID 32370233, 2020).
gastroenteropancreatic neuroendocrine tumors (6 papers, 2021 to 2025). "However, SSTR2 expression profiles in tumor cells and their association with the therapeutic efficacy of SSAs remains virtually unknown in gastrointestinal NETs (GI-NETs)." (PMID 35159042, 2022). "High-Am 153Sm was used to radiolabel DOTA-TATE, a well-established carrier molecule that specifically binds the somatostatin receptor 2 (SSTR2) that is highly expressed in gastroenteropancreatic neuroendocrine tumors (GEP-NETs)." (PMID 36559060, 2022). "We also demonstrate the potential of SSTR2 expression for prognosis and application with 68Ga-DOTA-peptide scanning, akin to the application of this imaging technique in gastrointestinal NETs and prostate, breast, and colorectal cancers." (PMID 33402692, 2021).
hypercortisolism (6 papers, 2016 to 2025). "In our study, the expression of SSTR2 or SSTR5 was detected in cases 1, 7, and 8, in which SSA had good effects on the control of hypercortisolism." (PMID 35265125, 2022). "The expression of SSTR2 is reduced by hypercortisolism and SRLs acting on SSTR2 are not effective in CD patients." (PMID 29881371, 2018).
pulmonary neuroendocrine tumors (6 papers, 2019 to 2024). "In a study of lung neuroendocrine tumors, SSTR2 expression in tissue correlated with octreotide scintigraphy in 71% of cases." (PMID 35198446, 2022). "Another study examined SSTR-2 expression retrospectively in 218 pulmonary neuroendocrine tumors, including 60 cases of LCNEC." (PMID 34513663, 2021). "Immunohistochemical analysis of SSTR-2 expression in pulmonary neuroendocrine tumors was reviewed retrospectively in a series of 218 “clinically aggressive cases” including 60 LCNEC." (PMID 34513663, 2021). "This study describes a potential method of increasing the membranous density of SSTR2 in pulmonary neuroendocrine tumors through the use of HDAC inhibitory compounds." (PMID 31163616, 2019). "Within the limits imposed by the relatively small cohort, our data suggest that SSTR2-IHC may surrogate SSTR-PET/CT in selected lung NET patients for clinical decision making when SSTR-PET/CT is not available." (PMID 35674739, 2022). "This retrospective study showed an overall good agreement between SSTR2-IHC on tissue and tumor uptake at 68Ga-SSA-PET/CT in patients with lung NET." (PMID 35674739, 2022). "This retrospective study showed an overall good agreement between SSTR2-IHC and tumor uptake at SSTR-PET/CT in lung NETs." (PMID 35674739, 2022). "SSTR2 and MGMT are well-recognized predictive markers for SSA and temozolomide efficacy, respectively, and are commonly discussed in gastroenteropancreatic and pulmonary neuroendocrine tumors." (PMID 39061142, 2024). "A long-term analysis of clinical outcome is needed to clarify whether SSTR2-IHC and SSTR-PET/CT findings are predictors of patient outcome, able to stratify lung NET patients with poor prognosis." (PMID 35674739, 2022). "It was established that PRRT was beneficial in patients with SSTR2-positive pancreatic, non-pancreatic GEP NETs, lung NETs and metastatic NETs with an unknown primary site." (PMID 38817893, 2024).